HVCN1 (hydrogen voltage gated channel 1)
Description:
Voltage-gated proton-selective channel that conducts outward proton currents in response to intracellular acidification. Lacks a canonical ion-channel pore domain and mediates proton permeability via its voltage sensor domain. Appears to play a dominant role in regulation of CO2/HCO3(-)/H(+) equilibrium in sperm flagellum. Prevents the acidification resulting from HCO3(-) synthesis and thus sustains high HCO3(-) levels inside sperm for capacitation. Provides for proton efflux that compensates for electron charge generated by NADPH oxidase activity either in the extracellular or phagosomal compartments, thus enabling the production of high levels of bactericidal reactive oxygen species during the respiratory burst. Opens when the pH of airway surface liquid exceeds 7 and contributes to respiratory epithelial acid secretion to maintain pH in the mucosa.
Synonyms: HV1; VSOP; MGC15619
Tractability: Antibody: UniProt places it where antibodies can reach, with high confidence; its Gene Ontology location is reachable by antibodies, with high confidence; UniProt predicts a signal peptide or a membrane-spanning region. PROTAC: ubiquitination databases record sites on it; its protein half-life has been measured.
Target class: Ion channel
Gene: Protein-coding gene on chromosome 12 (110,627,841 to 110,704,950, reverse strand). Ensembl gene ENSG00000122986.
Subcellular location: Cell membrane; Apical cell membrane; Cytoplasmic vesicle, phagosome membrane; Cell projection, cilium, flagellum membrane
Pathways (Reactome):
Immune System: Neutrophil degranulation; ROS and RNS production in phagocytes
Reproduction: Sperm Motility And Taxes
Gene Ontology:
Molecular function: identical protein binding; protein homodimerization activity; voltage-gated monoatomic cation channel activity; voltage-gated proton channel activity; monoatomic ion channel activity
Biological process: cellular response to pH; cellular response to zinc ion; proton transmembrane transport; regulation of acrosome reaction; regulation of intracellular pH; regulation of reactive oxygen species biosynthetic process; response to zinc ion; cell redox homeostasis; response to pH; monoatomic ion transport; transmembrane transport
Cellular component: membrane; phagocytic vesicle membrane; plasma membrane; sperm flagellum; secretory granule membrane; specific granule membrane; apical plasma membrane
Genetic constraint (gnomAD): Loss-of-function variants: 9 observed, 19.26 expected, observed/expected ratio (o/e) 0.47, 90% interval 0.28 to 0.82. The upper end of that interval is the gene's LOEUF score, 0.82, which puts it in group 3 of 6, group 1 being the genes least tolerant of losing a copy. Missense variants: 219 observed, 300.48 expected, observed/expected ratio (o/e) 0.73, 90% interval 0.65 to 0.81. Synonymous variants: 113 observed, 120.18 expected, observed/expected ratio (o/e) 0.94, 90% interval 0.81 to 1.1.
Homologues: Orthologues: chimpanzee HVCN1 (97% identical), macaque HVCN1 (93% identical), pig HVCN1 (88% identical), rabbit HVCN1 (85% identical), dog HVCN1 (83% identical), guinea pig HVCN1 (82% identical), mouse Hvcn1 (77% identical), rat Hvcn1 (74% identical), tropical clawed frog hvcn1 (44% identical), zebrafish hvcn1 (40% identical). Paralogues in human: TNS1 (21% identical), TNS3 (21% identical), TMEM266 (14% identical), PTEN (11% identical), TPTE (11% identical), TPTE2 (11% identical).
Diseases named in the same sentence as HVCN1 in open-access papers:
HVCN1 is named in the same sentence as 72 diseases in open-access papers, as found by Europe PMC text mining. Sharing a sentence is not in itself a finding about the gene and the disease. The quoted sentences say what the papers report.
Stroke (6 papers, 2019 to 2024). Sudden impairment of blood flow to a part of the brain due to occlusion or rupture of an artery to the brain. "Using transgenic Hvcn1 knockout (Hvcn1–/–) mice in which the Hvcn1 gene is deleted, many studies have shown that loss of the proton channel HVCN1 exhibits neuroprotective effects in CNS injury models, such as stroke, traumatic brain injury, and spinal cord injury." (PMID 34744634, 2021).
amyotrophic lateral sclerosis (3 papers, 2021 to 2026). Amyotrophic lateral sclerosis (ALS) is a neurodegenerative disease characterized by progressive muscular paralysis reflecting degeneration of motor neurons in the primary motor cortex, corticospinal tracts, brainstem and spinal cord. "To explore whether the protein level of HVCN1 is affected in neurodegenerative diseases, we first detected the HVCN1 protein level in SOD1G93A mice, a mostly used mouse model of amyotrophic lateral sclerosis (ALS)." (PMID 34744634, 2021).
ischemia (3 papers, 2020 to 2023). A hypoperfusion of the BLOOD through an organ or tissue caused by a PATHOLOGIC CONSTRICTION or obstruction of its BLOOD VESSELS, or an absence of BLOOD CIRCULATION. "Hv1, also known as HVCN1 (human voltage-gated proton channel) is a proton-selective ion channel whose action early after ischemia contributes to brain damage by providing the cancer cell with protons to compensate for the electron-transfer action of phagocytic cell NADPH oxidase." (PMID 34136464, 2021).
migraine (3 papers, 2020 to 2025). "TWAS genes with independent effects shared by subtypes of migraine and BP were consistent with findings for overall migraine at ITGB5, while identifying additional associations at HMOX2 for MA and BP, and HVCN1 and MANBA for MO and BP." (PMID 32632093, 2020).
autoimmune disorder (2 papers, 2021 to 2022). "A previous study has reported the development of autoimmunity in elderly Hvcn1-deficient mice, which might be compatible with the preferential survival of T cells (particularly of the CD4+ subset) with lower antigen affinity, which are, therefore, more likely to include autoreactive T cells." (PMID 35472029, 2022). "However, the Hvcn1-deficient line was followed for 14 months and neither developed spontaneous autoimmunity nor increased in the effector T cell (Teff) subset." (PMID 35472029, 2022).
chronic lymphocytic leukemia (2 papers, 2017 to 2024). "HVCN1 has expressed in BCR-signaling dependent malignant B cells, such as chronic lymphocytic leukemia (CLL) cells." (PMID 38789729, 2024).
Cognitive impairment (2 papers, 2024 to 2025). Abnormal cognition is characterized by deficits in thinking, reasoning, or remembering. "However, in mice receiving hippocampal injection of AAV-hTAU, Hvcn1 deletion significantly rescued tau-induced cognitive impairments." (PMID 41402464, 2025).
demyelination (2 papers, 2021 to 2024). "We showed that among HVCN1+ microglia/macrophages, the proportion of iNOS+ microglia/macrophages were about 80%, whereas the proportion Arg1+ microglia/macrophages were about 15%, indicating that within the focal demyelination lesion, the upregulated HVCN1 was mainly in iNOS+ microglia/macrophages." (PMID 34744634, 2021).
Crohn disease (1 paper, 2013). A gastrointestinal disorder characterized by chronic inflammation involving all layers of the intestinal wall, noncaseating granulomas affecting the intestinal wall and regional lymph nodes, and transmural fibrosis. "The expression levels of four genes identified by microarray screening (PLCB2, HVCN1, CTSS, and DEF8) and one purine/thiopurine related gene (NME6) correlated significantly with the clinical activity of Crohn’s disease." (PMID 23437289, 2013). "Five genes (NME6 from the purine/thiopurine network, PLCB2 of the RAC1 network, and HVCN1, CTSS, and DEF8) correlated with the Harvey-Bradshaw index of Crohn’s disease activity." (PMID 23437289, 2013).
cystic fibrosis (1 paper, 2021). Autosomal recessive disorder caused by pathogenic variants in the CFTR gene (cystic fibrosis transmembrane conductance regulator), which encodes a chloride and bicarbonate channel expressed in epithelial cells, and follow the diagnosis criteria. "Moreover, in cystic fibrosis patients who underwent ivacaftor therapy, the HVCN1 mRNA expression was significantly higher than baseline at 1-3 months and decreased after 6 months of treatment." (PMID 33936061, 2021).
heart failure (1 paper, 2022). Inability of the heart to pump blood at an adequate rate to meet tissue metabolic requirements. "Our results suggested a potential role of the HVCN1 channel in heart diseases, such as hypertrophy and heart failure associated with NOX-medicated ROS signaling pathways." (PMID 35372367, 2022).
Huntington disease (1 paper, 2021). Huntington disease (HD) is a rare neurodegenerative disorder of the central nervous system characterized by unwanted choreatic movements, behavioral and psychiatric disturbances and dementia. "To test whether HVCN1 is upregulated in other neurodegenerative diseases, using R6/2 mice, the mouse model of Huntington’s disease (HD), we found that in the cerebral cortex, the proportion of microglia/macrophages that expressed HVCN1 in all microglia/macrophages doubled." (PMID 34744634, 2021).
myocardial hypertrophy (1 paper, 2022). "In the long run, the activation of these pathways leads to myocardial hypertrophy via H2O2, which is the primary ROS regulated by HVCN1." (PMID 35372367, 2022).
peritonitis (1 paper, 2013). Inflammation of the peritoneum (tissue that lines the abdominal wall and covers most of the organs in the abdomen). "Consistently, in BALF eosinophils Hvcn1 expression level is also significantly higher (6.0-fold on average) than that in neutrophils isolated from a peritonitis model." (PMID 23705768, 2013).
tauopathy (1 paper, 2025). Neurodegenerative disorders involving deposition of abnormal tau protein isoforms (tau proteins) in neurons and glial cells in the brain. "In this study, we found that Hv1 is upregulated in both tauopathy mice and 3×Tg AD mice, accompanied by microglial activation, whereas Hvcn1 deletion or Hv1 inhibition restored microglial homeostasis." (PMID 41402464, 2025). "Further studies will be required to delineate the precise transcriptional mechanisms by which these pathways regulate Hvcn1 expression in microglia under tauopathy." (PMID 41402464, 2025).
cancer (17 papers, 2013 to 2025). A tumor composed of atypical neoplastic, often pleomorphic cells that invade other tissues. "A total number of 197 somatic HVCN1 mutations in various cancer types affecting 125 out of 273 residues (45.8%) of hHv1 were incorporated into our dataset after analyzing three different databases (COSMIC, TCGA, and ICGC)." (PMID 40001460, 2025). "Focusing on somatic cancer mutations of HVCN1, the gene of the human voltage-gated proton channel (hHV1), we analyzed five selected somatic mutations within the S4 segment to evaluate their possible influence on the cancer cell phenotype." (PMID 40001460, 2025). "The increased expression of this channel in some cancers has led to proposing Hvcn1 antagonists as potential therapeutics." (PMID 35472029, 2022).
tumor (16 papers, 2013 to 2025). "While the role of HVCN1 in tumor progression remains largely unexplored, our screening has identified HVCN1 as a potential prognostic marker for LGG." (PMID 38789729, 2024). "In conclusion, NHE1, CAR9, HVCn1, and V-type proton pumps act together on the plasma membrane of tumor cells to form a transmembrane pH gradient based on the inward H+ gradient." (PMID 36050306, 2022). "Previous studies had shown that knockdown of the HVCN1 gene resulted in slower tumor growth in a mouse model." (PMID 32374759, 2020). "CAR9 catalyzes the conversion of extracellular water and carbon dioxide to carbonic acid, which is decomposed into bicarbonate and H+; then, sodium bicarbonate is transported into tumor cells through the sodium bicarbonate cotransporter HVCn1, leaving H+ outside." (PMID 36050306, 2022). "Finally, the use of Hvcn1 inhibitors has been suggested as a potential therapeutic approach to malignancies, many of which aberrantly express this proton channel, likely as a mechanism of survival in the highly acidic tumor microenvironment." (PMID 35472029, 2022). "The effect of Hvcn1 on immune competence, as described here and including the studies with one of the most promising Hvcn1 inhibitors, suggests that this approach might affect not only the tumor but also the anti-tumor immune response, at least during the priming stage." (PMID 35472029, 2022). "Studies have confirmed that NHE1, HVCn1, and V-type proton pumps can promote the proliferation, migration, and drug resistance of tumor cells, and silencing NHE1 or SLC4A7 significantly reduced tumor growth in a mouse xenograft model." (PMID 36050306, 2022). "Moreover, we found that IBC tumour-infiltrating B cells also presented high levels of immature signals, which was reflected mainly in the significantly high expression of five molecules, CD22, FCRL1, FCRLA, HVCN1, and SP100, in IBC tumour-infiltrating B cells." (PMID 40624675, 2025).
infection (4 papers, 2021 to 2024). The state of being infected such as from the introduction of a foreign agent such as serum, vaccine, antigenic substance or organism. "Intriguingly, they also demonstrated that following fungal lung infection with Candida albicans, airway inflammation was more severe in Hvcn1-/- mice than in wild-type controls, despite being able to efficiently clear the infection." (PMID 34441020, 2021).
neurodegenerative disease (3 papers, 2021 to 2026). A disorder of the central nervous system characterized by gradual and progressive loss of neural tissue and neurologic function. "Taken together, these results indicate that HVCN1 is upregulated in microglia/macrophage in multiple injuries and neurodegenerative diseases of the CNS." (PMID 34744634, 2021).
heart disease (2 papers, 2019 to 2022). "In summary, the present study highlights the importance of HVCN1 in cardiac function and may present a novel target associated with heart diseases." (PMID 35372367, 2022). "The study highlights the importance of HVCN1 in cardiac function and may present a novel target associated with heart diseases." (PMID 35372367, 2022).
inflammation (1 paper, 2021). Aberrant reaction of the microcirculation characterized by movement of fluid and leukocytes from the blood into extravascular tissues. "To further test whether the expression of HVCN1 in the brain is affected by a systemic injury, which also involves the brain, we induced systemic inflammation in adult mice by an i.p. injection of LPS and 12 h later when brain inflammation has been established." (PMID 34744634, 2021).
HVCN1 also shares sentences with these, for which no sentence is quoted: ischemic stroke (16 papers); breast carcinoma (8); multiple sclerosis (6); infertile (5); Parkinson disease (4); Alzheimer disease (3); brain ischemia (3); colorectal cancer (3); glioblastoma multiforme (3); leukemia (3); neurological diseases (3); autoimmune disease (2); brain injury (2); injury (2); Pain (2); Acidosis (1); adenocarcinoma (1); adenoma (1); allergic asthma (1); Anosmia (1); asthenozoospermia (1); asthma (1); breast tumor (1); cardiomyopathy (1); Cerebral ischemia (1); channelopathies (1); chronic gastritis (1); colon cancer (1); colorectal adenoma (1); colorectal tumor (1).
A further 21 diseases each share a sentence with HVCN1 in 1 paper.